IL6 (interleukin 6)
Diseases named in the same sentence as IL6 in open-access papers (continued):
Sharing a sentence is not in itself a finding about the gene and the disease.
Anxiety (continued). "However, performing the exploratory analyses separately for males and females, revealed that in males the IL6 rs1800795 G allele increased the risk for RRIs only in association with maternal pregnancy-specific anxiety." (PMID 33828172, 2021). "Our findings thus suggested that the differential expressions of BDNF and IL-6 after CSDS may contribute to less anxiety and less despair observed in GHS-R1a-deficient mice than in WT control mice." (PMID 31057357, 2019). "The IL-1β and IL-6 were positively associated to the anger and the anxiety state, respectively." (PMID 29445205, 2018). "Pioglitazone demonstrated efficacy in improving both core (social withdrawal and repetitive behaviors) and associated (irritability, hyperactivity, and anxiety) autism symptoms and did significantly decrease the pro-inflammatory cytokine IL-6 and increase the anti-inflammatory cytokine IL-10." (PMID 30498564, 2018). "The low-grade levels of these systemically circulating inflammatory markers were secondly significantly associated with behavior; We found levels of IL-6, IL-12p70 and IL-17A to significantly correlate with memory, anxiety, anhedonia and species-typical behavior." (PMID 25133574, 2014). "The discrepant results on the association of IL-6 and symptoms of anxiety may be explained by the fact that individual types of anxiety disorders are associated with different bio-behavioral mechanisms and not all of them are associated with chronic low-grade inflammation." (PMID 37840785, 2023). "In mice, SFDF improved memory and learning, alleviated anxiety-like behavior, reduced IL-6, TNF-α, and lipid peroxidation, and enhanced antioxidant defenses." (PMID 41705257, 2026). "Mediation analyses indicated that global small-worldness mediated the relationship between IL-6 levels and poor sleep quality, whereas the local efficiency of SFGmed.L mediated the associations between IFN-γ levels and anxiety and cognitive performance." (PMID 42311681, 2026). "HH induced enhanced anxiety-like behaviors and reduced spontaneous activity, accompanied by elevated levels of L-1β, IL-6, and TNF-α in both serum and hypothalamus." (PMID 41222826, 2025). "We found that anxiety scores were positively correlated with serum IL-6 levels (R = 0.16, P = 0.02)." (PMID 41050477, 2025). "Anti-inflammatory Agents: Emerging evidence supports the use of IL-6 inhibitors and NSAIDs to target inflammation-related pathways that exacerbate both anxiety and metabolic dysfunction." (PMID 40218134, 2025). "Using the elevated plus maze, treated mice exhibited reduced anxiety-like behavior and lower IL-6 and TNF-α systemic levels in blood samples." (PMID 40342368, 2025). "A study found that quercetin administration decreases brain concentrations of inflammatory factors, including IL-1β, IL-6, and NF-kB, and mitigates anxiety-like behaviors in rats with lipopolysaccharide-induced chronic neuroinflammation." (PMID 40333577, 2025). "Open field and elevated plus maze tests revealed heightened anxiety-like behaviors in the STAg offspring, which were largely reversed by IL-6 inhibition." (PMID 41150800, 2025). "The observed correlation between lower anxiety scores and reduced inflammation (e.g., lower IL-6) in our study supports the well-established bi-directional communication between the psychological state and inflammatory pathways." (PMID 41332436, 2025). "Studies have shown that the experimental administration of tumor necrosis factor alpha (TNF-α), interleukin-1 beta (IL-1β), and IL-6 results in a depressive effect, including anxiety, drowsiness, and fatigue, in humans." (PMID 40746874, 2025). "Higher empathy scores reported by asthmatic patients in JSE correlate with reduced patients’ anxiety, lower serum IL-6 levels, improved self-efficacy, and better sleep quality." (PMID 40873791, 2025). "Chronic IBS symptoms are associated with gut–brain signaling disruptions and changes in IL-6 levels, contributing to enhanced memory and anxiety." (PMID 40696692, 2025).
Anxiety (continued). "These cells release cytokines and chemokines, such as TNF-α, IL-1β, IFN-γ, IL-6, iNOS, etc., which ultimately lead to neuronal death and trigger anxiety." (PMID 39905541, 2025). "This investigation reveals that inflammatory markers like TNF-α and IL-6—triggered by chemotherapy—as well as hormonal fluctuations intensify psychological distress, including anxiety, depressive symptoms, and social isolation." (PMID 40688105, 2025). "Our findings are in line with previous EFT studies showing reductions in inflammatory markers like IL-6 and cortisol alongside decreased anxiety, supporting a psychoneuroimmunological model in which emotional regulation promotes immune recovery." (PMID 41020118, 2025). "Systematic inhibition of IL-6 signaling by antibody-mediated neutralization ameliorates anxiety and social interaction deficits in this mouse model, but did not rescue impairments in social recognition, social novelty, or repetitive behaviors." (PMID 41150800, 2025). "Gyps significantly suppresses proinflammatory mediators (IL-1β, IL-6, NF-κB) in LPS-induced neuroinflammation and anxiety models, demonstrating therapeutic potential for neuroinflammation-associated anxiety behaviors." (PMID 41181612, 2025). "Specifically, empathy reduces patient anxiety, which in turn directly enhances self-efficacy and sleep quality, both of which influence IL-6 concentrations." (PMID 40873791, 2025). "Increased levels of cytokines, such as IL-6 and TNF-α, have been linked to anxiety-related brain regions including the prefrontal and limbic systems." (PMID 40964431, 2025). "IL-6 exemplifies this convergence most clearly, tracking with depressive severity and anxiety symptoms in neuropsychiatric conditions while simultaneously sustaining keratinocyte activation in psoriatic plaques." (PMID 41277234, 2025). "Anxiety and self-efficacy, as well as anxiety and sleep quality, act as chain-mediated factors linking empathy to serum IL-6 levels." (PMID 40873791, 2025). "Accordingly, increased TNF‐α and IL‐6 levels simulated by LPS would increase anxiety and enhance the severity of cardiovascular injury." (PMID 39264256, 2024). "On the other hand, stress stimuli such as tension, anxiety, and surgery stimulate macrophages and endothelial cells to produce inflammatory cytokines such as interleukin-6 (IL-6)." (PMID 38807080, 2024). "In another study, it was reported that suppression of the IL‐6 increment would decrease the level of anxiety." (PMID 39264256, 2024). "In our study, a correlation was observed between the increase in TNF‐α and IL‐6 levels and anxiety in hyperglycaemic rats on either diet." (PMID 39264256, 2024). "It has been demonstrated that treatment with fenofibrate significantly attenuated prenatal VPA-induced anxiety and low exploratory activity by reducing IL-6 and TNF-α in the prefrontal cortex." (PMID 39720795, 2024). "After 4 months of nutritional therapy, the intervention group showed a marked decrease in the serum concentration of IL-6, with also a concomitant improvement in the state of anxiety, and the functional capabilities of patients." (PMID 38921006, 2024). "Key findings include significant reductions in IL-6 levels and state anxiety, improvements in metabolic health markers like fat oxidation and muscle mass, and positive shifts in lipid metabolism." (PMID 39203859, 2024). "The results which combined network pharmacological analysis and molecular docking showed that the effects of treating PTSD and anxiety of beta-sitosterol, Tenulin, Fumarine, and Stigmasterol were associated with AKT1 and IL-6." (PMID 37986356, 2023). "This supports our data and suggests that early and chronic overexpression of IL6 can decrease anxiety-like behaviors." (PMID 38075266, 2023). "Susceptible-EPM rats have elevated levels of IL-6 (p = 0.0158) and IL-10 (p = 0.0352) in the PFC suggesting that higher anxiety is associated with chronic neuroinflammation." (PMID 37064304, 2023).
Anxiety (continued). "In the active disease group, IL-6 level was lower in the subjects experiencing anxiety symptoms but statistically insignificant (1.00 pg/ml vs. 2.81 pg/ml, p-value 0.573)." (PMID 37916198, 2023). "A positive correlation was found between anxiety and IL-6 at baseline (P=0.046) and on D3 (P=0.037)." (PMID 37878890, 2023). "In our study, the constitutive overexpression of IL6 in the CNS in aged female heterozygous GFAP-IL6 mice led to the dysregulation of anxiety-like behavior, locomotor activity and spatial learning and memory." (PMID 38075266, 2023). "Pregnant women with severe anxiety and accompanying depressive symptoms showed a significant increase in serum levels of IL-6 and TNF-α." (PMID 37637801, 2023). "Laboratory findings have shown that abnormal secretion of inflammatory markers such as TNF-α and interleukin-6 (IL-6) can lead to elevated anxiety levels." (PMID 38264647, 2023). "The prevalence and severity of anxiety were significantly associated with PCT, IL-6, and CRP (p<0.05)." (PMID 37621784, 2023). "There is a correlation between increased IL-6 levels and the development of anxiety in experimental animals." (PMID 37687297, 2023). "IL1β, TNFα and IL6 were evaluated in the medial prefrontal cortex, nucleus acumens and amygdala, structures known to play pivotal roles in motivational, social or anxiety behavioral processes." (PMID 36675275, 2023). "In VPA-induced ASD model mice, HRW administration improved ASD-like behaviors such as social behavior and pain sensation as well as anxiety-like behavior and memory impairment and IL-6 and TNF-α inflammatory cytokines." (PMID 36982559, 2023). "In a pilot trial, the effects of coconut oil and EGCG on IL-6, anxiety, and functional impairment in MS patients were evaluated." (PMID 37229273, 2023). "Increase in anxiety like behavior, increase in Bacteroidetes, decrease in Firmicutes/Bacteroidetes ratio, increase in intestinal levels of IL-6, TNF-α, 5-HT, and decrease in corticotropin-releasing hormone, BDNF, and neuropeptide Y in the brain." (PMID 37324381, 2023). "We previously reported that LPS-induced anxiety-like behavior in adult male mice positively correlated with IL-6 and CCL2 levels in the plasma and chemokine (CXCL10 and CCL2) expression in the brain." (PMID 36698151, 2023). "The deficiency of SCFAs exaggerates neuroinflammation by increasing IL-1β and IL-6 expression in the hippocampus, thereby promoting anxiety through inhibiting BDNF-GABA signal pathway." (PMID 37273529, 2023). "The offspring of those females whose IL-6 levels were elevated during pregnancy showed more anxiety-like behaviors at the age of 11 months." (PMID 37840785, 2023). "Behavioral tests and biochemical analyses indicated that diabetic rats showed significantly increased anxiety and depressive-like behavioral deficits, brain oxidative stress and pro-inflammatory cytokines levels (IL-1β, IL-6 and TNF-α)." (PMID 35408607, 2022). "In this study, HET was shown to ameliorate anxiety-like behavior (through the light-dark test and hole-board test) and decrease IL-6 levels in LPS-treated mice." (PMID 36034871, 2022). "IL-6 is also commonly elevated in acute encephalopathy, a clinical syndrome that itself can contribute to the development of anxiety-like states via fragmented memories and impaired cognitive processing of distressing experiences." (PMID 36100846, 2022). "Our study revealed that HET ameliorated LPS-induced anxiety-like behavior and inhibited IL-6 release in vivo and in vitro." (PMID 36034871, 2022). "Compared to the VILI + Saline-treated mice, the VILI + α-IL-6 mice entered more and spent more time in open arms suggesting less anxiety and avoidance like behavior (p = 0.044 and p = 0.003 respectively)." (PMID 36100846, 2022). "Cytokine production, particularly IL-1β and IL-6 production, by these cells contributes to anxiety-like behavior during social stress." (PMID 35216112, 2022).
Anxiety (continued). "The same relationship between symptoms and IL-6 concentrations was also found for anxious women (defined by endorsing a score on the State Trait Anxiety Inventory <34)." (PMID 35836664, 2022). "In summary, this study provides first evidence of potentially reversible systemic IL-6-mediated neural injury in the amygdala and hippocampus with corresponding acute delirium- and anxiety-like neuropsychiatric functional impairments in a murine model of VILI." (PMID 36100846, 2022). "norBNI pretreatment blocked or significantly reduced blast-induced increase in serum and brain cytokines, including IL-6, at 4 h post exposure and aversive/anxiety-like behavioral dysfunction at 1-month post-exposure." (PMID 36463243, 2022). "Individuals with familial Mediterranean fever, chronic pain, and an increased inflammatory response (augmentation of interleukin-6, C-reactive proteins, and fibrinogen blood levels) will experience anxiety symptoms at higher rates than the general population." (PMID 36159294, 2022). "In animal models, astrocytic IL-6 mediated anxiety, and there is ample evidence for a role of glia, both astrocytes and microglia, in sleep regulation and neuropsychiatric disorders [for a review see]." (PMID 35614970, 2022). "We evaluated the association of putative functional and tag SNPs within IL1B, IL2, and IL6 with aggression case status, parent‐reported internalizing problems, self‐reported anxiety symptoms, and self‐reported depressive symptoms in our sample." (PMID 36168941, 2022). "In this study, we demonstrate that systemic IL-6 inhibition reverses VILI-induced neural injury of the amygdala and hippocampus and associated acute delirium- and anxiety-like neuropsychiatric functional impairments." (PMID 36100846, 2022). "The repeated administration of HET prevented anxiety-like behavior and decreased serum IL-6 levels in LPS-treated mice." (PMID 36034871, 2022). "In conclusion, our study demonstrated that HET inhibits cytokine release, suggesting that the effect of HET on inflammation-induced anxiety-like behavior involves an anti-inflammatory action through IL-6 suppression in the early stages of inflammation." (PMID 36034871, 2022). "A previous study reported that anxiety-like behavior in obese mice was associated with increased levels of TNF-α, IL-1β, and IL-6 in the brain." (PMID 35209199, 2022). "Consistent with previous literature reports, our results found that IL-6 and TNF-α were significantly important in their association with pregnancy anxiety and function as drivers of inflammation." (PMID 34360332, 2021). "Partial improvement in the locomotor activity and anxiety-like behaviors by The upregulation of IL-1β and IL-6 in the hippocampus region with the restoration of surgery-induced microglial over-activation." (PMID 34497516, 2021). "It was found that MAPK, AKT1, and IL-6 in the serum of patients with anxiety were all increased, and there was a significant positive correlation between anxiety severity and sleep quality." (PMID 34660782, 2021). "Ileal Nfkb expression also coordinated with hippocampal Ccl5 and IL-6 production to predict anxiety-like behavior." (PMID 34248950, 2021). "Elevated IL-6 and TNF-α have been shown to increase the activity of the amygdala—the region associated with anxiety and depressive symptoms." (PMID 34575258, 2021). "The specific effects of increased IL-6 activity on behavior remain elusive but evidence from studies with genetically modified mice suggests that IL-6 is involved in the regulation of anxiety-like and depressive-like behaviors." (PMID 34067897, 2021). "The purpose of this study was to investigate anxiety and the role of the immune system, specifically IL-6 positive neurons in this animal model." (PMID 33683478, 2021). "The regression analysis showed that the relationship between anxiety and stimulated IL‐6 for healthy controls approached significance after accounting for possible confounding variables." (PMID 31199593, 2020).
Anxiety (continued). "The serum TNF-α and IL-6 concentration were higher in patients with IBS-D than in the healthy controls, and the anxiety scores were associated with a high concentration of TNF-α." (PMID 33092151, 2020). "Religious psychological concepts also indicate that spirituality mediates the indirect influence of anxiety on IL-6." (PMID 33255406, 2020). "As a result of this link between the high levels of IL-6 and the perception of anxiety, we can see that anxiety disorders are found amongst the most common psychiatric disorders associated with MS." (PMID 31979305, 2020). "In a national database with 2861 participants, higher C reactive protein (CRP) levels were similarly associated with somatic and cognitive symptoms of anxiety in male subjects, while IL-6 and TNF-a levels were associated with somatic symptoms of anxiety." (PMID 32824625, 2020). "In this context, several reports have shown increased levels of cytokines, such as interleukin-1β (IL-1β) and interleukin-6 (IL-6) in experimental models of anxiety-depression." (PMID 31578381, 2019). "A laboratory‐based study with middle‐aged, healthy participants showed that task‐related increases in anxiety predicted increases in IL‐6 concentrations." (PMID 30666661, 2019). "The first one demonstrated that the stress-induced increase in hypothalamic IL-6 and microglia activation were suppressed following benzodiazepine treatment, ameliorating anxiety, and social avoidance behavior in adult mice." (PMID 31534953, 2019). "The Δvalue of the anxiety state score was positively correlated with Δvalue of IL-6 in plasma and saliva." (PMID 29445205, 2018). "Non-specific peripheral immune activation caused by injection of lipopolysaccharide in healthy volunteers increases serum IL-6 levels as well as inducing low mood, anxiety and reduced cognitive performance." (PMID 29197507, 2018). "The levels of IL-6 are significantly higher in patients with a diagnosis of affective, anxiety, adjustment, psychotic, obsessive-compulsive, and Tourette disorders as well as depressed patients." (PMID 30662368, 2018). "Regarding IL-6, this cytokine has been reported to be higher in depressed subjects than in non-depressed subjects, which is in line with our results since IL-6 mRNA levels were altered in subjects with both anxiety and mood disorders." (PMID 30504920, 2018). "Immunoactivation in mice and healthy volunteers by injection of lipopolysaccharide has been reported to increase circulating proinflammatory cytokine levels (IL-1β, IL-6) as well as producing symptoms of anxiety and reduced cognitive performance." (PMID 27476619, 2017). "In the general population, anxiety symptoms were associated with increase of several inflammation markers, including C-reactive protein, TNF-α, and IL-6, even after adjusting for multiple confounding factors." (PMID 26881136, 2016). "We have previously shown that compared to floxed mice, Ast-IL-6 KO mice exhibit a number of altered behaviors under normal (basal) conditions, including changes in activity, anxiety and learning; a prosurvival role of astrocytic IL-6 is also apparent." (PMID 27196935, 2016). "Basal CRP, IL-6 andTNF-α, as well as most individual LPS-stimulated inflammation markers (IL-6,IL-8, IL-10, IL-18, MCP-1, MIP-1α, MIP-1β, MMP2 and TNF-β) weresignificantly associated with depressive and anxiety symptom severity." (PMID 27244234, 2016). "The biomarkers had somewhat distinct patterns of associations with the different scales, with IL6 being more strongly associated with scores on the depressive and anxiety scales; and TBARS being associated with the anxiety and conduct scales." (PMID 27489945, 2016). "Although results are mixed, some animal studies showed a relationship between increased proinflammatory cytokines levels including interleukin-6 and IL-1β and anxiety-like behaviors." (PMID 26881136, 2016).